FHL2 (four and a half LIM domains 2)
Diseases named in the same sentence as FHL2 in open-access papers (continued):
Sharing a sentence is not in itself a finding about the gene and the disease.
lung carcinoma (6 papers, 2013 to 2023). "Similar to the outcomes above, high FHL2 expression demonstrated a close association with lung adenocarcinoma, stage II, T2, and M0 lung carcinoma." (PMID 36227138, 2022). "FHL2 demonstrated moderate diagnostic ability for lung cancer (AUC = 0.857)." (PMID 36227138, 2022). "Nevertheless, the diagnostic and prognostic value of FHL2 in lung cancer is still unclear." (PMID 36227138, 2022). "In this study, we aimed to demonstrate that lung cancer patients with high FHL2 expression have worse overall survival (OS) and relapse-free survival (RFS)." (PMID 36227138, 2022). "Relationship between FHL2 expression and clinicopathological parameters in patients with lung cancer." (PMID 36227138, 2022). "The high expression level of FHL2 in lung cancer can be used as an independent predictor of prognosis in clinical practice." (PMID 36227138, 2022). "Herein, we assessed the correlation between FHL2 expression in lung cancer and clinicopathologic characteristics through analyzing data from The Cancer Genome Atlas (TCGA) database." (PMID 36227138, 2022). "FHL2 was highly expressed in lung cancer cells and related to their proliferation, migration, and invasion ability." (PMID 36227138, 2022). "We found that FHL2 contributes to lung cancer progression by inducing glycolysis and promoting unfolded protein responses." (PMID 36227138, 2022). "Consistently, FHL2 was highly expressed in lung cancer patients." (PMID 36227138, 2022). "This suggests that FHL2 may affect lung cancer progression by regulating Glycolysis and inducing unfolded protein response." (PMID 36227138, 2022). "In addition, in vitro experiments also showed that FHL2 is highly expressed in lung cancer cells, and the high expression of FHL2 is related to the enhancement of the proliferation, migration, and invasion ability." (PMID 36227138, 2022). "The qRT-PCR was used to detect the FHL2 expression in lung cancer cells." (PMID 36227138, 2022). "GSEA analysis revealed findings on the mechanism by which FHL2 affects lung cancer progression." (PMID 36227138, 2022). "In conclusion, FHL2 has great potential to predict the prognosis of lung cancer." (PMID 36227138, 2022). "The nomogram results indicated that FHL2 could be used to predict the survival of lung cancer patients." (PMID 36227138, 2022). "However, no study reported the expression level and prognostic significance of FHL2 in lung cancer." (PMID 35154287, 2022). "More importantly, we plotted ROC curves to assess the value of FHL2 in predicting one-, three-, and even five-year RFS in lung cancer patients." (PMID 36227138, 2022). "Similarly, RUNX2 is a coregulator of three TFs (E2F3, FHL2, and TWIST1) that also appear in the NSCLC lung cancer regulatory network." (PMID 36551878, 2022). "The second suggests a cooperative function between RUNX2 and three transcription factors (BRCA1, FOXM1, and RUNX1) important for the specific regulation of lung cancer establishment and progression, along with three transcription factors (E2F3, FHL2, and TWIST1) of the NSCLC-GRN." (PMID 36551878, 2022). "Moreover, RUNX2 is a coregulator of three of the transcriptional regulators identified in the NSCLC-GRN (i.e., E2F3, FHL2, and TWIST1), suggesting a cooperative function of these TFs in lung cancer, which has not been studied experimentally in lung cancer." (PMID 36551878, 2022).
lung fibrosis (6 papers, 2013 to 2024). "FHL2 has already been implicated in different inflammatory process in mice as well as in humans, where FHL2 was proposed to be a marker of lung fibrosis." (PMID 28243234, 2017). "Experiments have shown that FHL2 inhibitors can significantly delay the progression of pulmonary fibrosis." (PMID 38784225, 2024). "Collectively, these data indicated that CFH and FHL2 are involved in the pulmonary fibrosis and activation of fibroblasts induced by bleomycin and TGFβ1, respectively." (PMID 38784225, 2024). "In this study, we identified four potential biomarkers (FHL2, HPCAL1, RNF182, and SLAIN1) and evaluated the potential pathogenic role of SLAIN1 in idiopathic pulmonary fibrosis." (PMID 37783761, 2023). "The purpose of this work was to study the potential supportive effect of FHL2 on the development of BLM-induced lung fibrosis." (PMID 24260575, 2013). "Telocytes might be one of the key players in preventing the development of inflammation and fibrogenesis in chronic lung inflammation, since bleomycin-induced lung fibrosis is suppressed by FHL2 by attenuating lung inflammation." (PMID 24826900, 2014). "Therefore, the macrophage pools of WT and FHL2-KO mice were depleted by injection of clodronate-liposomes and lung fibrosis was scored after BLM application." (PMID 24260575, 2013). "However, in contrast to CTHRC1, FHL2 has been reported to positively regulate the expression of collagen types I and III in an FHL2-induced BLM-treated lung fibrosis model; this process tended to involve acceleration of lung inflammation rather than direct FHL2-induced fibrotic mechanisms." (PMID 31185973, 2019). "FHL2, HPCAL1, RNF182, and SLAIN1 were identified as biomarkers of idiopathic pulmonary fibrosis using LASSO logistic regression, RF, and SVM-RFE algorithms." (PMID 37783761, 2023). "In summary, this research successfully pinpointed four promising biomarkers (FHL2, HPCAL1, RNF182, and SLAIN1) and investigated the potential involvement of SLAIN1 in the pathogenesis of idiopathic pulmonary fibrosis." (PMID 37783761, 2023). "Here, we present evidence that FHL2 does not promote bleomycin-induced lung fibrosis, but rather suppresses this process by attenuating lung inflammation." (PMID 24260575, 2013). "In this study, we showed that the absence of the adaptor protein FHL2 aggravated BLM-mediated lung fibrosis." (PMID 24260575, 2013).
atherosclerosis (5 papers, 2014 to 2026). A disease characterized by the build-up of fatty material and calcium deposition in the arterial wall resulting in partial or complete occlusion of the arterial lumen. "Recently, it has been reported that deficiency of FHL2 may inhibit atherosclerosis after a cholesterol-enriched diet." (PMID 24736599, 2014). "We focus on a cytoskeletal protein, Four-and-a-half LIM protein 2 (FHL2), which is consistently enriched in endothelial tissues experiencing atherosclerosis-prone disturbed flow, both in vitro and in vivo." (PMID 42192127, 2026). "Strikingly, this atherosclerosis-like phenotype requires the force-sensitive binding of FHL2 to the actin cytoskeleton." (PMID 42192127, 2026). "The four and a half LIM domain protein 2 (FHL2) is a member of the four and a half LIM domain (FHL) gene family, and it is associated with cholesterol‐enriched diet‐promoted atherosclerosis." (PMID 31714683, 2020). "Recent studies have focused on the role of FHL2 in blood vessel walls, where it is involved in vascular lesion formation, and development of atherosclerosis." (PMID 28714941, 2017). "We demonstrate that increased FHL2 expression is necessary and sufficient to induce hallmarks of atherosclerosis-like endothelial phenotypes, including aberrant cell morphology, discontinuous cell junctions, hypercontractility, and increased tissue permeability." (PMID 42192127, 2026). "Notably, FHL2 depletion has shown beneficial effects in mitigating high fat diet–induced atherosclerosis and arterial stenosis." (PMID 38664060, 2024). "Here, we investigated the role of FHL2 in a model of restricted blood flow‐induced atherosclerosis." (PMID 31714683, 2020). "However, in response to PDGF, which is up‐regulated by restricted blood flow‐induced atherosclerosis, FHL2 is induced during HASMC proliferation and migration and interacts with AKT, subsequently modulating ERK1/2 and p38 phosphorylation." (PMID 31714683, 2020).
colorectal cancer (5 papers, 2010 to 2022). A primary or metastatic malignant neoplasm that affects the colon or rectum. "Taken together, this work identified KLF8-induced FHL2 activation as a novel and critical signaling mechanism underlying human breast/colorectal cancer invasion and metastasis." (PMID 26320172, 2015). "We and others have implicated FHL2 as an oncogenic factor in colorectal cancer (CRC), squamous cell carcinoma, melanoma, glioblastoma and prostate cancer." (PMID 26320172, 2015). "It is suggested that the interaction between FoxK1 and FHL2 promotes the growth and metastasis of colorectal cancer cells." (PMID 35903069, 2022). "And in colorectal cancer, knockdown FHL2 repressed the FOXK1-dependent cell growth and metastasis." (PMID 33092075, 2020). "However, the effects of the interaction of FOXK1 and FHL2 on the development, progression and prognosis of colorectal cancer (CRC) remain to be defined." (PMID 27892920, 2016). "In colorectal cancer, further examination of FHL2 expression in a large panel of samples may permit to determine if FHL2 could be used as a marker for stage classification of the disease." (PMID 20442768, 2010). "Consistent with an early report showing nuclear expression of FHL2 in gastrointestinal cancerous tissues, our data further indicate that high level expression and nuclear accumulation of FHL2 in human colorectal cancer might reflect disease progression towards the malignant state." (PMID 20442768, 2010). "Our data highlight FHL2 as important molecule in mediation of the transformation process and suggest that disruption of the FHL2 signalling may provide a viable and specific strategy for therapeutic intervention in colorectal cancer." (PMID 20442768, 2010). "In human colorectal carcinoma but not in low-grade dysplasia, we detected up-regulation and enhanced nuclear localization of FHL2, indicating the activation of FHL2 during the development of malignancy." (PMID 20442768, 2010).
glioblastoma (5 papers, 2016 to 2023). The most malignant astrocytic tumor (WHO grade IV). "Previous reports have shown that FHL2 facilitates cell proliferation in glioblastoma, gastric, colon, and cervical cancers, but inhibits neuroblastoma and myeloid malignancies." (PMID 36227138, 2022). "Previous reports have shown that FHL2 facilitates cell proliferation in glioblastoma, gastric, colon, and cervical cancers." (PMID 36227138, 2022). "Although several studies have shed light on the relevance of FHL2 in terms of CNS-related pathology, including epilepsy and glioblastoma, the understanding of the regulatory role of FHL2 is yet to be fully appreciated." (PMID 32256309, 2020). "Specifically, FHL2 interacts with EGFR to promote glioblastoma growth." (PMID 36227138, 2022).
liver fibrosis (5 papers, 2013 to 2023). "Key molecules associated with liver fibrosis and inflammation (Cd34, Epcam, S100a6, Fhl2, Itgax, and Retnlg) were up-regulated at both the gene and protein levels." (PMID 38076459, 2023). "A previous study revealed that deficiency of FHL2 aggravates liver fibrosis in mice, where it negatively regulates TGF-β1 expression." (PMID 35910357, 2022). "Still and, in summary, these data clearly indicate that mice with Fhl2 deficiency were more prone to hepatic fibrosis in the BDL model." (PMID 31963815, 2020). "Furthermore, the expression of transforming growth factor-β (Tgf-β), the most prominent pro-fibrogenic cytokine in liver fibrosis, was significantly higher in the livers of Fhl2-deficient compared to the wt mice that were exposed to BDL." (PMID 31963815, 2020). "Deficiency of FHL2 results in aggravation of murine liver fibrosis." (PMID 23311569, 2013). "We show that deficiency of FHL2 results in aggravation of murine liver fibrosis." (PMID 23311569, 2013). "These pathological processes are closely intertwined, and it is difficult to dissect whether the enhanced fibrosis was indirectly caused by the more pronounced injury and inflammation or whether FHL2 also directly impacts hepatic fibrosis and HSCs." (PMID 31963815, 2020). "This study shows for the first time that FHL2 is crucial in experimental liver fibrosis." (PMID 23311569, 2013). "Interestingly FHL2−/− mice developed significantly aggravated liver fibrosis compared to respective wt control mice as demonstrated in Sirius Red stain." (PMID 23311569, 2013). "In the present study aggravated liver fibrosis was especially associated with upregulated collagen III expression in mice lacking FHL2 and subjected to CCl4-treatment." (PMID 23311569, 2013). "FHL2−/− mice displayed aggravated liver fibrosis compared to wt mice." (PMID 23311569, 2013). "We therefore hypothesize, that FHL2 acts probably as a coactivator regulating important target genes in the setting of liver fibrosis as well." (PMID 23311569, 2013). "We here investigated the role of FHL2 in the setting of experimental and clinical liver fibrosis." (PMID 23311569, 2013). "In our human liver fibrosis samples studied, MFB showed a strong nuclear and cytoplasmatic expression of FHL2." (PMID 23311569, 2013). "Furthermore, a recent study showed that FHL2 interacts with TGF-β1 and inhibits its expression and is involved in kidney fibrosis, liver fibrosis, and lung fibrosis." (PMID 35910357, 2022).
pancreatic cancer (5 papers, 2017 to 2022). "The role of FHL-2 in tumors is bidirectional, whereby overexpression of FHL-2 has been observed in colorectal, gastric, and pancreatic cancer, while it has been reported to be downregulated in HCC." (PMID 34305593, 2021).
cervical carcinoma (4 papers, 2020 to 2023). A carcinoma arising from either the exocervical squamous epithelium or the endocervical glandular epithelium. "FHL2 is a zinc finger transcription factor associated with several cancers, including ovarian and cervical cancers." (PMID 37226243, 2023). "FHL2 knockdown downregulated the expression of key proteins in the PI3K/AKT/mTOR signaling pathway, thereby promoting apoptosis and inhibiting the proliferation of cervical cancer cells." (PMID 36004205, 2022).
diabetes (4 papers, 2016 to 2022). "We have analyzed FHL2 expression level in human glomerular samples and found it is up-regulated in almost all kind of proteinuric kidney diseases, including hypertension, diabetes, FSGS, membranous nephritis, IgA nephropathy, and nephritis caused by lupus or vasculitis." (PMID 31040292, 2019). "In addition, methylation of KLF14, FHL2 and GNPNAT1 was associated with lower diabetes risk in the Botnia prospective study." (PMID 27029739, 2016). "Our data seem controversial but different measures were compared: FHL2 mRNA levels in pancreatic islets from individuals without and with high HbA1c or diabetes vs methylation status of the FHL2 gene in blood in a follow-up study." (PMID 35802167, 2022).
Graves disease (4 papers, 2020 to 2023). Graves' disease is an autoimmune disorder that leads to overactivity of the thyroid gland (hyperthyroidism).It is caused by an abnormal immune system response that causes the thyroid gland to produce too much thyroid hormones. "While altered DNA methylation leading to decreased prediction accuracy was found for both TRIM59 and FHL2 in the group of Graves’ disease, indicating differences in how various diseases affect the methylation of age-correlated CpGs." (PMID 37621446, 2023). "Patients with Alzheimer’s Disease showed normal FHL2 methylation, whereas in the blood of patients with Grave’s Disease a marked hypomethylation was found for one of the FHL2 CpG sites." (PMID 34685595, 2021). "However, the CpGs in TRIM59 showed hypermethylation in the group of early onset Alzheimer’s disease as well as Graves’ disease patients while the CpGs in FHL2 showed hypomethylation in the latter." (PMID 37621446, 2023).
hypertrophic cardiomyopathy (4 papers, 2014 to 2025). A condition in which the myocardium is hypertrophied without an obvious cause. "Evidence shows that FHL2 protein levels are lower in patients with hypertrophic cardiomyopathy (HCM), and FHL2 overexpression protects phenylephrine- or endothelin-1-induced hypertrophy in cardiac myocytes." (PMID 35910357, 2022). "Importantly, the interactions between these binding partners were impaired by mutations in nesprin-2, telethonin, and FHL-2 identified in EDMD with DCM and hypertrophic cardiomyopathy patients." (PMID 38569934, 2024). "Importantly we also showed that binding between nesprin-2/telethonin and nesprin-2/FHL-2 was impaired by nesprin-2, telethonin, and FHL-2 mutations identified in patients with EDMD with DCM and patients with hypertrophic cardiomyopathy (HCM), implicating these complexes as key to cardiac function." (PMID 38569934, 2024).
lung adenocarcinoma (4 papers, 2022 to 2025). A carcinoma that arises from the lung and is characterized by the presence of malignant glandular epithelial cells. "Similarly, cancer-associated fibroblast-derived FHL2 promotes angiogenesis and metastasis in lung adenocarcinoma by activating osteopontin secretion." (PMID 41258071, 2025). "The further subgroup analysis revealed that high FHL2 expression was associated with poor OS of patients with lung adenocarcinoma (P = 0.0110), lung squamous cell carcinoma (P = 0.0160), stage II (P = 0.0059), T2 (P < 0.0001), N2 (P = 0.0033) and M0 (P = 0.0048)." (PMID 36227138, 2022). "Lung adenocarcinoma patients had higher FHL2 expression levels (P < 0.01) than lung squamous cell carcinoma patients." (PMID 36227138, 2022). "The expression of FHL2 is significantly elevated in certain malignant tumors, including cholangiocarcinoma (CHOL), colon adenocarcinoma (COAD), esophageal carcinoma (ESCA), head and neck squamous cell carcinoma (HNSC), lung adenocarcinoma (LUAD), LUSC, and pancreatic adenocarcinoma (PAAD)." (PMID 40482916, 2025).